SEPTIN11 (septin 11)
Description:
Filament-forming cytoskeletal GTPase. May play a role in cytokinesis (Potential). May play a role in the cytoarchitecture of neurons, including dendritic arborization and dendritic spines, and in GABAergic synaptic connectivity (By similarity). During Listeria monocytogenes infection, not required for the bacterial entry process, but restricts its efficacy.
Synonyms: SEPT11; FLJ10849; Septin-11
Tractability: Small molecule: a structure with a bound ligand is known. PROTAC: ubiquitination databases record sites on it.
Gene: Protein-coding gene on chromosome 4 (76,949,747 to 77,040,384, forward strand). Ensembl gene ENSG00000138758.
Subcellular location: Cytoplasm, cytoskeleton; Synapse; Cell projection, dendritic spine; Cell projection, axon
Subcellular location (Human Protein Atlas): Cytosol; Annulus; Mid piece; Primary cilium; Principal piece
Gene Ontology:
Molecular function: protein binding; GTPase activity; molecular adaptor activity; GTP binding
Biological process: cytoskeleton-dependent cytokinesis; intracellular protein localization
Cellular component: septin complex; stress fiber; cell division site; microtubule cytoskeleton; septin ring; axon; cytoskeleton; dendritic spine; synapse
Genetic constraint (gnomAD): Loss-of-function variants: 23 observed, 49.86 expected, observed/expected ratio (o/e) 0.46, 90% interval 0.33 to 0.65. The upper end of that interval is the gene's LOEUF score, 0.65, which puts it in group 2 of 6, group 1 being the genes least tolerant of losing a copy. Missense variants: 374 observed, 534.55 expected, observed/expected ratio (o/e) 0.7, 90% interval 0.64 to 0.76. Synonymous variants: 172 observed, 191.28 expected, observed/expected ratio (o/e) 0.9, 90% interval 0.79 to 1.02.
Homologues: Orthologues: macaque SEPTIN11 (99% identical), guinea pig SEPTIN11 (99% identical), mouse Septin11 (99% identical), pig SEPTIN11 (99% identical), chimpanzee SEPTIN11 (97% identical), dog SEPTIN11 (97% identical), rat Septin11 (92% identical), tropical clawed frog septin11 (92% identical), rabbit SEPTIN11 (89% identical), Drosophila melanogaster Septin2 (68% identical), Caenorhabditis elegans unc-61 (44% identical), Drosophila melanogaster Septin1 (35% identical). Paralogues in human: SEPTIN6 (82% identical), SEPTIN8 (79% identical), SEPTIN10 (73% identical), SEPTIN14 (63% identical), SEPTIN7 (41% identical), SEPTIN2 (33% identical), SEPTIN5 (33% identical), SEPTIN3 (32% identical), SEPTIN1 (32% identical), SEPTIN9 (31% identical), SEPTIN12 (28% identical), TMEM250 (5% identical).
Diseases named in the same sentence as SEPTIN11 in open-access papers:
SEPTIN11 is named in the same sentence as 16 diseases in open-access papers, as found by Europe PMC text mining. Sharing a sentence is not in itself a finding about the gene and the disease. The quoted sentences say what the papers report.
frontotemporal lobar degeneration (2 papers, 2011 to 2025). "Here, we describe the identification of septin 11 (SEPT11), an enriched component of detergent-resistant fractions in frontotemporal lobar degeneration with ubiquitin-immunoreactive inclusions (FTLD-U), using large-scale unbiased proteomics approaches." (PMID 22126117, 2011).
thyroid cancer (2 papers, 2016 to 2017). "SEPT11 (septin-11) is a GTP-binding protein organized in filaments and was detected in FTC-133 thyroid cancer cells." (PMID 26818711, 2016).
Insulin resistance (1 paper, 2019). Increased resistance towards insulin, that is, diminished effectiveness of insulin in reducing blood glucose levels. "SEPT11 mRNA was positively correlated with markers of insulin resistance in adipose tissue, and silencing of septin-11 muted insulin signaling and insulin-induced lipid accumulation in adipocytes." (PMID 31105878, 2019).
tumor (4 papers, 2017 to 2023). "In contrast, IHC using a commercial anti-septin-11 antibody or a commercial anti-GABAB2 receptor antibody showed no staining of the tumor tissues of patient 1, though antibody functionality was demonstrated by IHC with mouse neuronal tissue sections (data not shown)." (PMID 36997937, 2023).
SEPTIN11 also shares sentences with these, for which no sentence is quoted: cancer (3 papers); atherosclerosis (1); bipolar disorder (1); breast carcinoma (1); glioma (1); hematological malignancies (1); hepatocellular carcinoma (1); leukemia (1); osteosarcoma (1); proteopathies (1); renal cell carcinoma (1); schizophrenia (1).